H2AC6 (H2A clustered histone 6)
Description:
Core component of nucleosome. Nucleosomes wrap and compact DNA into chromatin, limiting DNA accessibility to the cellular machineries which require DNA as a template. Histones thereby play a central role in transcription regulation, DNA repair, DNA replication and chromosomal stability. DNA accessibility is regulated via a complex set of post-translational modifications of histones, also called histone code, and nucleosome remodeling.
Synonyms: H2AFL; HIST1H2AC; H2A/l; dJ221C16.4
Tractability: Small molecule: a structure with a bound ligand is known. PROTAC: UniProt records ubiquitination sites on it; ubiquitination databases record sites on it.
Gene: Protein-coding gene on chromosome 6 (26,124,145 to 26,139,116, forward strand). Ensembl gene ENSG00000180573.
Subcellular location: Nucleus; Chromosome
Subcellular location (Human Protein Atlas): Nucleoplasm
Pathways (Reactome):
Gene expression (Transcription): B-WICH complex positively regulates rRNA expression; DNA methylation; ERCC6 (CSB) and EHMT2 (G9a) positively regulate rRNA expression; MLL4 and MLL3 complexes regulate expression of PPARG target genes in adipogenesis and hepatic steatosis; NoRC negatively regulates rRNA expression; PRC2 methylates histones and DNA; RNA Polymerase I Promoter Escape; RNA Polymerase I Promoter Opening; RUNX1 regulates genes involved in megakaryocyte differentiation and platelet function; RUNX1 regulates transcription of genes involved in differentiation of HSCs; Regulation of endogenous retroelements by KRAB-ZFP proteins; Regulation of endogenous retroelements by Piwi-interacting RNAs (piRNAs); Regulation of endogenous retroelements by the Human Silencing Hub (HUSH) complex; SIRT1 negatively regulates rRNA expression; Transcriptional regulation by small RNAs
Chromatin organization: CHD1 and CHD2 subfamily; CHD6, CHD7, CHD8, CHD9 subfamily; ChAHP complex assembly; HATs acetylate histones; HDACs deacetylate histones; Interaction of NuRD complexes with transcription factors; NuRD complex assembly; RMTs methylate histone arginines
Cell Cycle: Condensation of Prophase Chromosomes; Deposition of new CENPA-containing nucleosomes at the centromere; Inhibition of DNA recombination at telomere; Packaging Of Telomere Ends
DNA Repair: Cleavage of the damaged purine; Cleavage of the damaged pyrimidine; Recognition and association of DNA glycosylase with site containing an affected purine; Recognition and association of DNA glycosylase with site containing an affected pyrimidine
Disease: Defective pyroptosis; Dengue Virus-Host Interactions; HCMV Early Events; HCMV Late Events
Metabolism of proteins: Amyloid fiber formation; Metalloprotease DUBs; UCH proteinases; Ub-specific processing proteases
Signal Transduction: Activated PKN1 stimulates transcription of AR (androgen receptor) regulated genes KLK2 and KLK3
and 15 more pathways
Gene Ontology:
Molecular function: protein binding; structural constituent of chromatin; DNA binding; protein heterodimerization activity
Biological process: negative regulation of cell population proliferation; chromatin organization; heterochromatin formation
Cellular component: extracellular exosome; nucleoplasm; nucleus; nucleosome; chromosome
Genetic constraint (gnomAD): Loss-of-function variants: 5 observed, 7.26 expected, observed/expected ratio (o/e) 0.69, 90% interval 0.36 to 1.43. That is too few expected variants to judge how well the gene tolerates losing a copy. Missense variants: 154 observed, 191.62 expected, observed/expected ratio (o/e) 0.8, 90% interval 0.7 to 0.92. Synonymous variants: 146 observed, 83.73 expected, observed/expected ratio (o/e) 1.74, 90% interval 1.52 to 1.95.
Homologues: Orthologues: chimpanzee H2AC6 (100% identical), macaque H2AC6 (100% identical), pig H2AC6 (100% identical), rabbit H2AC6 (100% identical), rat Hist1h2ah (99% identical), Drosophila melanogaster His2A:CG31618 (86% identical), Drosophila melanogaster His2A:CG33808 (86% identical), Drosophila melanogaster His2A:CG33814 (86% identical), Drosophila melanogaster His2A:CG33817 (86% identical), Drosophila melanogaster His2A:CG33820 (86% identical), Drosophila melanogaster His2A:CG33823 (86% identical), Drosophila melanogaster His2A:CG33826 (86% identical), and 13 more. Paralogues in human: H2AC25 (99% identical), H2AC11 (98% identical), H2AC13 (98% identical), H2AC15 (98% identical), H2AC16 (98% identical), H2AC17 (98% identical), H2AC18 (98% identical), H2AC19 (98% identical), H2AC4 (98% identical), H2AC8 (98% identical), H2AC7 (98% identical), H2AC12 (97% identical), and 15 more.
Diseases named in the same sentence as H2AC6 in open-access papers:
H2AC6 is named in the same sentence as 16 diseases in open-access papers, as found by Europe PMC text mining. Sharing a sentence is not in itself a finding about the gene and the disease. The quoted sentences say what the papers report.
colon cancer (1 paper, 2022). "Otherwise, the protein expression levels of TRADD, H2AC6, VDAC3, JMJD7-PLA2G4B, TRAF2, and DAPK1 in colon cancer tissues and normal tissues in the HPA database were shown, which were consistent with the expression levels of these genes in RNA levels." (PMID 36505813, 2022).
neoplasm (2 papers, 2024 to 2025). A benign or malignant tissue growth resulting from uncontrolled cell proliferation. "CKS1B+ neoplasm, C16orf89+ neoplasm, CST6+ neoplasm, H2AC6+ neoplasm and MTND2P13+ neoplasm all demonstrate heightened tumour stemness." (PMID 38946232, 2024).
H2AC6 also shares sentences with these, for which no sentence is quoted: bladder cancer (1 paper); breast carcinoma (1); cancer (1); chronic lymphocytic leukaemia (1); colorectal cancer (1); COVID-19 (1); erythroleukemia (1); esophageal adenocarcinoma (1); glioma (1); hepatocellular carcinoma (1); infection (1); pancreatic cancer (1); pulmonary disease (1); T-cell acute lymphoblastic leukemia (1).